RNU7-54P (RNA, U7 small nuclear 54 pseudogene)
Synonyms: U7.54
Gene: Small nuclear RNA gene on chromosome 7 (128,443,449 to 128,443,510, reverse strand). Ensembl gene ENSG00000238590.
Homologues: Orthologues: macaque U7 (94% identical), pig U7 (81% identical). Paralogues in human: RNU7-26P (85% identical), RNU7-2P (85% identical), RNU7-52P (85% identical), RNU7-23P (84% identical), U7 (84% identical), RNU7-1 (82% identical), RNU7-11P (82% identical), RNU7-12P (82% identical), RNU7-188P (82% identical), RNU7-35P (82% identical), RNU7-3P (82% identical), RNU7-65P (82% identical), and 142 more.